PNLDC1 (PARN like ribonuclease domain containing exonuclease 1)
Description:
3'-exoribonuclease that has a preference for poly(A) tails of mRNAs, thereby efficiently degrading poly(A) tails. Exonucleolytic degradation of the poly(A) tail is often the first step in the decay of eukaryotic mRNAs and is also used to silence certain maternal mRNAs translationally during oocyte maturation and early embryonic development. May act as a regulator of multipotency in embryonic stem cells (By similarity). Is a critical factor for proper spermatogenesis, involved in pre-piRNAs processing to generate mature piRNAs.
Synonyms: HsPNLDC1; FLJ40240; dJ195P10.2; Trimmer; SPGF57
Tractability: Antibody: UniProt predicts a signal peptide or a membrane-spanning region.
Gene: Protein-coding gene on chromosome 6 (159,800,249 to 159,820,704, forward strand). Ensembl gene ENSG00000146453.
Subcellular location: Endoplasmic reticulum membrane
Gene Ontology:
Molecular function: poly(A)-specific ribonuclease activity; 3'-5'-RNA exonuclease activity; RNA binding; nucleic acid binding
Biological process: nuclear-transcribed mRNA poly(A) tail shortening; piRNA processing; spermatogenesis; priRNA 3'-end processing; siRNA 3'-end processing; developmental process
Cellular component: endoplasmic reticulum; endoplasmic reticulum membrane; nucleus
Genetic constraint (gnomAD): Loss-of-function variants: 69 observed, 81.06 expected, observed/expected ratio (o/e) 0.85, 90% interval 0.7 to 1.04. The upper end of that interval is the gene's LOEUF score, 1.04, which puts it in group 4 of 6, group 1 being the genes least tolerant of losing a copy. Missense variants: 613 observed, 675.5 expected, observed/expected ratio (o/e) 0.91, 90% interval 0.85 to 0.97. Synonymous variants: 276 observed, 259.47 expected, observed/expected ratio (o/e) 1.06, 90% interval 0.96 to 1.17.
Homologues: Orthologues: chimpanzee PNLDC1 (99% identical), macaque PNLDC1 (96% identical), dog PNLDC1 (88% identical), pig PNLDC1 (88% identical), rabbit PNLDC1 (86% identical), mouse Pnldc1 (85% identical), guinea pig PNLDC1 (79% identical), rat Pnldc1 (75% identical), Caenorhabditis elegans parn-1 (21% identical). Paralogues in human: PARN (29% identical), TOE1 (16% identical).
Diseases named in the same sentence as PNLDC1 in open-access papers:
PNLDC1 is named in the same sentence as 9 diseases in open-access papers, as found by Europe PMC text mining. Sharing a sentence is not in itself a finding about the gene and the disease. The quoted sentences say what the papers report.
Azoospermia (3 papers, 2022 to 2024). Absence of any measurable level of sperm,whereby spermatozoa cannot be observed even after centrifugation of the semen pellet. "Recently multiple PNLDC1 variants with defective piRNA processing have been detected in azoospermia in men, establishing a PNLDC1-specific monogenic cause of human infertility." (PMID 39312580, 2024). "PNLDC1 is essential for male fertility in mice, with its loss leading to spermatogenic arrest at the elongated spermatid stage, culminating in azoospermia." (PMID 39312580, 2024). "Loss-of-function mutations in human PNLDC1 cause azoospermia in men." (PMID 39312580, 2024). "Specifically, PNLDC1, a PARN-like 3′-to-5′ exonuclease located at the membrane of the mitochondria in a mouse, is critical to the processing of piRNAs and PNLDC1 disrupted in mice would lead to azoospermia and male infertility ultimately." (PMID 35361267, 2022). "Men with dysfunctional PNLDC1 and nonobstructive azoospermia showed a concomitant loss of PIWIL1 expression." (PMID 35725394, 2022). "While PNLDC1 expression in HIR testes is downregulated, no increase after GnRHa treatment was observed, which is consistent with the notion that this gene is not directly involved in the development of azoospermia in cryptorchid patients." (PMID 35725394, 2022).
male infertility (2 papers, 2022 to 2024). The inability of the male to effect fertilization of an ovum after a specified period of unprotected intercourse. "Strikingly, postnatal germline conditional deletion of Pnldc1 in mice that disrupt pre-pachytene and pachytene piRNA trimming causes transposon activation and male infertility." (PMID 39312580, 2024). "Recent research has reported various PNLDC1 variants in azoospermic men, suggesting a monogenic cause of human male infertility." (PMID 39312580, 2024).
Cryptozoospermia (1 paper, 2024). A type of oligozoospermia in which spermatozoa can be detected in an ejaculate only after centrifugation and inspection of the pellet. "The two PNLDC1 variant carriers exhibited cryptozoospermia and, fittingly, the testicular biopsy of M1125 revealed only a few tubules with elongated spermatids while TESE was negative." (PMID 39122675, 2024).
pontocerebellar hypoplasia type 7 (1 paper, 2024). "Functions of these enzymes are central to human health, with TOE1 mutations associated with Pontocerebellar Hypoplasia Type 7 (PCH7), PARN mutations with Dyskeratosis Congenita and other human disorders, PNLDC1 mutations with azoospermia, and USB1 mutations with Poikiloderma with neutropenia." (PMID 38194449, 2024).
cancer (3 papers, 2021 to 2025). A tumor composed of atypical neoplastic, often pleomorphic cells that invade other tissues. "Former studies pointed that PNLDC1 was related to survival in CRC patients, and PNLDC1 expressed higher in normal colorectal tissues than in cancer tissues." (PMID 35361267, 2022). "PNLDC1, SLC5A1, and SYNM were then identified as hub genes that were associated with both platinum response status and prognosis, which was further validated by the Fudan University Shanghai cancer center (FUSCC) cohort." (PMID 35361267, 2022). "However, PNLDC1 was more highly expressed in the normal colorectal tissues than in the cancer tissues." (PMID 33868829, 2021). "PNLDC1 (10.14) and AMPD1 (10.05-fold), involved in RNA processing and purine metabolism, may disrupt cancer cell homeostasis, impairing growth." (PMID 40430278, 2025).
tumor (1 paper, 2020). "PNLDC1 mRNA was altered in several tumor types by analyzing more than 6,000 adult and pediatric tumors." (PMID 33224957, 2020). "Some of the identified prognostic DE RBPs have been reported associated with tumor progression, such as RBM47, LUZP4, AFF3, PPARGC1A, PPARGC1B, PABPC3, and PNLDC1." (PMID 33224957, 2020).
PNLDC1 also shares sentences with these, for which no sentence is quoted: Infertility (1 paper); renal dysfunction (1); spermatogenic failure (1).